SMAD2 (SMAD family member 2)
Diseases named in the same sentence as SMAD2 in open-access papers (continued):
Sharing a sentence is not in itself a finding about the gene and the disease.
liver cancer (continued). "In a liver cancer model, SMAD2/3 is upregulated in cells undergoing senescence, in keeping with our results." (PMID 28841682, 2017). "Moreover, BUB1 promotes the proliferation and vertical migration ability of liver cancer cells by activating phosphorylation of SMAD2." (PMID 36787437, 2023). "Propofol can reduce the expression of PCNA, CD34, and PATK proteins in patients, thereby increasing the activity and content of transforming growth factor TGF-β1 by 12% and 20%, respectively, thereby inhibiting the proliferation rate of liver cancer cells by 10% through the Smad2 signaling pathway." (PMID 34323647, 2021). "Propofol can increase the activity and content of transforming growth factor-β1 by 12% and 20%, respectively, and then inhibit the proliferation rate of liver cancer cells by 10% through the Smad2 signaling pathway, and exponentially increase the apoptotic number of liver cancer cells." (PMID 34323647, 2021). "The present study demonstrated that BUB1 may promote liver cancer cell proliferation by activating the phosphorylation of SMAD2." (PMID 32269624, 2020). "Similarly, we found that the expression of Smad2/3 and Smad4 directly promotes liver cancer spherogenesis and consequently confers these cells with high stemness and CSC properties." (PMID 28415588, 2017). "The mutation of other genes, including β-catenin, SMAD2, SMAD4, p16 INK4a, and Cyclin D1, may also be implicated in liver cancer." (PMID 22091434, 2011). "Therefore, BUB1 may promote proliferation of liver cancer cells by activating phosphorylation of SMAD2, and BUB1 may serve as a potential target in the diagnosis and/or treatment of liver cancer." (PMID 32269624, 2020). "SMAD2 and SMAD3 correlated with autophagy-related scores (based on ATG12, ATG7, ATG3, ATG5, ATG4B, PIK3C3, PRKAA2, and GABARAPL1) in liver cancer." (PMID 37790613, 2023). "The Cancer Genome Atlas (TCGA) database was used for comprehensively analyzing the prognostic values of SMAD2 and SMAD3 in liver cancer." (PMID 37790613, 2023). "SMAD2 and SMAD3 significantly positively correlated with autophagy-related scores in liver cancer patients in TCGA." (PMID 37790613, 2023). "It is necessary to clarify the function of Smad1/5/8 and the interactions of the Smad2/3 and Smad1/5/8 pathways during the TGF-β-induced EMT and cell invasion in liver cancer." (PMID 35580109, 2022). "Discussed and verified the effect of isopropanol on the growth of liver cancer cells and the role of TGF-β1/Smad2 signaling pathway." (PMID 34323647, 2021). "In conclusion, JR inhibits liver cancer cells migration and invasion through epithelial mesenchymal transition (EMT) inhibition via Smad2/3 dependent and independent pathways, suggesting it is an effective therapeutic strategy against HCC metastasis." (PMID 30174709, 2018). "The correlation between SMAD2, SMAD3, and autophagy-related scores in liver cancer was explored." (PMID 37790613, 2023). "SMAD2 and SMAD3 correlated with autophagy-related scores in liver cancer." (PMID 37790613, 2023). "The prognostic values of SMAD2 and SMAD3 in liver cancer were explored." (PMID 37790613, 2023). "In our study, SMAD2 and SMAD3 were hazardous factors in liver cancer." (PMID 37790613, 2023). "To identify the key genes associated with DYRK1A-mediated promotion of TGF-β/SMAD signalling, we generated a Venn diagram, which showed that there were 25 overlapping genes among those coexpressed with DYRK1A, SMAD2 and SMAD3 in liver cancer and DYRK1A-interacting proteins." (PMID 35655269, 2022).
myocardial infarction (32 papers, 2015 to 2026). Gross necrosis of the myocardium, as a result of interruption of the blood supply to the area, as in coronary thrombosis. "Baicalin improves cardiac function and myocardial fibrosis in rats with myocardial infarction, possibly through the p38 phosphorylation and TGFβ1/Smad2 pathway, exhibiting a protective effect against MI/R injury." (PMID 38659000, 2024). "Salvianolate treats myocardial infarction by inhibiting the TGF-β1/Smad2/3 and TXNIP/NLRP3 inflammasome signaling pathways." (PMID 36909150, 2023). "Resveratrol supplement reduced NLRP3 inflammasome activity, decreased TGF-β1 production, and downregulated the p-SMAD2/SMAD2 expression in a rat model of acute myocardial infarction, thus protecting the heart against cardiac fibrosis." (PMID 37504569, 2023). "On the other hand, our previous studies have shown that levels of angiotensin II, which acts upstream of TGF-β-Smad2/3 signaling, is increased in mice with myocardial infarction (MI)." (PMID 32334642, 2020). "Although TGF-β activates both Smad2 and Smad3 in vivo, CF-specific Smad2/3 knockout mice demonstrated that the observed effects on cardiac fibrosis and scar formation following pressure overload or myocardial infarction, respectively, were mainly attributed to Smad3." (PMID 35626694, 2022). "SMAD2 has been proved to act importantly in MIRI or myocardial infarction." (PMID 34632932, 2021). "Moreover, TGF-β1 is overexpressed in the heart in a high-cholesterol-fed porcine model of myocardial infarction, and its downstream Smad2 and Smad3 are activated, thereby increasing collagen synthesis and the levels of Col1a1, Col3a1, and α-SMA." (PMID 34485393, 2021). "Furthermore, using a coronary artery ligation model of myocardial infarction in rats, we observed increases in the levels of protein markers of fibrosis, autophagy and Smad2 phosphorylation in whole scar tissue lysates." (PMID 25789971, 2015). "Curcumin has been shown to protect the heart from cardiac fibrosis after myocardial infarction by inhibiting macrophage–fibroblast cross talk in the acute phase post-injury and retrained the activation of IL18-TGFβ1-p-SMAD2/3 signaling in the mice model." (PMID 37504569, 2023). "Salvianolate reduces atrial fibrillation by inhibiting the TGF-β1/Smad2/3 and TXNIP/NLRP3 inflammasome signaling pathways in rats after myocardial infarction, thereby inhibiting atrial fibrosis." (PMID 36909150, 2023). "In an animal model of myocardial infarction (MI), MMP14 expressed in macrophages induced their release of TGFβ1, which subsequently resulted in activation of SMAD2-mediated EndMT pathways in nearby ECs through paracrine signaling." (PMID 34566697, 2021). "A recent study showed that another member of BMP family, BMP-7, facilitates the recovery of cardiac function after acute myocardial infarction through attenuating TGF-β1 (transforming growth factor-β1) and its downstream signaling pathway Smad2/355." (PMID 30082698, 2018).
glioblastoma (29 papers, 2014 to 2026). The most malignant astrocytic tumor (WHO grade IV). "Tumor electric field therapy (TEFT) inhibits glioblastoma progression by suppressing the TGF‐β/SMAD2/3/STAT3/C1R axis to reverse epithelial‐mesenchymal transition (EMT)." (PMID 41489302, 2026). "Taken together, these data suggest that compound 7 inhibits GMT in glioblastoma cells through the TGF-β1/SMAD2/3 pathway." (PMID 39135794, 2024). "In our study, MICAL2 was widely expressed and coexpressed with TGF receptor-type I (TGFRI) in glioblastoma and was positively correlated with the expression of p-Smad2, which lies downstream of TGF-β." (PMID 34868922, 2021). "Here, we found that MICAL2 interacts with TGF receptor-type I (TGFRI) and promotes the proliferation and migration of glioblastoma through the TGF-β/p-Smad2/EMT-like signaling pathway." (PMID 34868922, 2021). "VEGF was released in glioblastoma by TGFβ regulation, leading to the phosphorylation of SMAD2, SMAD3, and SMAD1/5/8 and increased VEGF release." (PMID 34067437, 2021). "To interrogate the conclusion that SMAD2(+) identified the proliferation fraction of glioblastoma cells, we performed double-label immunohistochemistry for pSmad1 or pSmad2 and PCNA in human glioblastoma surgical specimens (n = 4, 15 HPF/specimen)." (PMID 31602000, 2019). "PI3K/Akt and Smad2/3 signaling cascades possess opposing effects in NAG-1-induced glioblastoma cell apoptosis." (PMID 24759784, 2014). "A prominent induction of PI3K/Akt and Smad2 phosphorylation was detected in all six glioblastoma cell lines." (PMID 24759784, 2014). "The PI3K inhibitors promoted NAG-1-induced glioblastoma cell apoptosis, while siRNAs to Smad2 and Smad3 decreased the apoptosis rate." (PMID 24759784, 2014). "NAG-1 could induce the phosphorylation of PI3K/Akt and Smad2/3 in all six tested glioblastoma cell lines, except Smad3 phosphorylation in A172 and LN-229 cell lines." (PMID 24759784, 2014). "Recently, it was shown that chelerythrine reduces the protein expression of p-ERK1/2 and p-Smad2/3 and inhibits the TGF-β1-ERK1/2/Smad2/3-Snail/ZEB1 signaling pathway, thereby decreasing glioblastoma progression in U251 and T98G cell lines." (PMID 40286187, 2025). "Their research demonstrated that CHE effectively suppresses the TGFB1-ERK1/2/Smad2/3-Snail/ZEB1 signaling pathway, thereby impeding the development of glioblastoma." (PMID 38675484, 2024). "In glioblastoma cells (U87 MG), a positive feedback loop was also reported, in which Cripto regulates its own expression through ALK4/SMAD2/3 signaling." (PMID 32517087, 2020). "In glioblastoma, tumor cell growth is significantly inhibited by ACY-1215 through transforming growth factor β receptor signaling, which induces SMAD2 phosphorylation and increased P21 expression." (PMID 30050135, 2018). "In human neuroepithelial and glioblastoma cells, higher levels of myostatin and activin lead to a synchronous increase in the phosphorylated Smad2 and non-phosphorylated FOXO3 levels." (PMID 40149435, 2025). "Finally, glioblastoma patients express high levels of USP4, which in turn can enhance the expression of TβRI, resulting in increased phospho-SMAD2." (PMID 38256140, 2024). "Moreover, TGF-β–induced endogenous Smad2/3 activity was prolonged in TNF-α–treated glioblastoma cells, which suggests that TNF-α sustained TGF-β–induced TGF-β/Smad activation in glioblastoma cells." (PMID 25971746, 2015). "Here we reported that NAG-1 overexpression could activate PI3K/Akt and Smad2/3 signaling cascades in glioblastoma cells, and that NAG-1-induced apoptosis was enhanced by PI3K inhibitors and decreased by siRNAs to Smad2 and Smad3." (PMID 24759784, 2014). "The PI3K inhibitors and Smad2/3 siRNAs had no proapoptotic effects on Ad-Con infected glioblastoma cells." (PMID 24759784, 2014).
glioblastoma (continued). "However, it is proposed in glioblastoma that high MSH6 promotes aggressive cell phenotypes more directly by acting through a MSH6-CXCR4-TGFβ1 feedback loop that regulates p-STAT3/Slug and p-Smad2/3/ZEB2 signalling pathways." (PMID 36482191, 2023). "Phosphorylated Smad2 levels have been proposed as a negative prognostic marker in glioblastoma." (PMID 25849941, 2015). "In glioblastoma cells, TGFβ activates p38 MAPK and ATF2 but does not induce JNK phosphorylation; furthermore, inhibition of p38 MAPK decreases TGFβ-induced phosphorylation of ATF2 and Smad2." (PMID 24674138, 2014).
prostate carcinoma (29 papers, 2013 to 2026). A carcinoma that arises from epithelial cells of the prostate gland. "WWP1 negatively regulates the TGF-β tumor suppressor pathway by targeting components like Smad2 and TβRI for ubiquitination and degradation, thereby enhancing prostate cancer (PCa) cell proliferation (Massagué and Like, 1985)." (PMID 39949609, 2024). "WWP1 negatively regulates this pathway by ubiquitinating and degrading critical components like Smad2 and TβRI, which in prostate cancer (PCa) results in WWP1 overexpression that inhibits TGF-β-induced gene expression and promotes cell proliferation." (PMID 39949609, 2024). "SMAD2 mRNA levels were significantly downregulated in prostate carcinomas compared to normal prostate tissue, and even more so at metastatic compared to primary tumor sites." (PMID 31160676, 2019). "Overexpression of miR-486-5p in prostate cancer results in downregulation of SMAD2 while promoting proliferation, migration, and colony formation." (PMID 31842336, 2019). "We further experimentally validated that miR-486-5p directly suppresses the expression of PTEN, FOXO1 and SMAD2, and then contributes to prostate cancers, which makes it subject to complex regulation by miRNAs." (PMID 29069829, 2017). "Similarly, decreased expression of miR-505-3p contributes to prostate cancer progression by targeting SMAD2 and SMAD3, and stimulating migration and invasion." (PMID 31842336, 2019). "However, survivin is downregulated by TGFβ in prostate cancer by downregulating downstream SMAD2/3, thereby inducing cell apoptosis, suggesting that TGFβ-regulated survivin expression depends on cellular context." (PMID 29212257, 2017). "On the other side, in prostate cancer, miR-486-5p induces different oncogenic pathways through the negative regulation of tumor suppressors such as FOXO1, PTEN, and SMAD2." (PMID 35337095, 2022). "miR-19a-3p, which targets the downstream effectors of TGFβ signaling, SMAD2, and SMAD4, is known to inhibit prostate cancer cell invasion and migration." (PMID 34503200, 2021). "A corresponding loop has been observed in prostate cancer cells, where Cx43 was shown to regulate the activity of TGF-induced signaling pathways via the interference with the sequestration of Smad2/3 on microtubules." (PMID 33923767, 2021). "In prostate cancer, miR-582-5p can inhibit tumor metastasis by targeting several components of TGF-β signaling, including SMAD2, SMAD4, TGFBRI, and TGFBRII." (PMID 34978519, 2021). "Apigenin has been reported to counteract the effects of TGF-β in other contexts as well, such as TGF-β-induced fibroblast to myofibroblast transition in human lungs and TGF-β-induced VEGF expression in human prostate carcinoma cells by inhibiting Src/FAK/Akt and thereby Smad2/3 phosphorylation." (PMID 26397139, 2015).
cardiac hypertrophy (28 papers, 2013 to 2025). "The difference in cardiac hypertrophy responses of Tgfbr1/2 and Smad2 and Smad3 (Smad2/3) specific cardiac fibroblasts deficient mice to pressure overload stimulation indicates that atypical TGF-β signal also plays an effective role in cardiac fibroblast-mediated remodeling after chronic injury." (PMID 37065745, 2023). "Mechanistically, we found that TGFBR1 gene silencing decreased myocardial collagen synthesis through the Smad2/3 signaling pathway and inhibited cardiac hypertrophy through the p38/MAPK–JNK1/2 signaling pathway in HFpEF mice." (PMID 40880411, 2025). "The study assessed two of the multiple signaling pathways involved in the development of cardiac hypertrophy, focusing on the molecule chosen as a therapeutic agent, Smad2/3." (PMID 41154653, 2025). "Constitutive overexpression of the human tumor suppressor A20 suppressed TAK-1-induced collagen synthesis and TAK-1-dependent Smad2/3/4 activation in murine hearts, protecting against cardiac hypertrophy and fibrosis." (PMID 35326728, 2022). "Ang II infusion activates several signaling pathways including AKT/mTOR, TGF-β/Smad2/3, and NF-κB through Ang II type receptor (AT1R), causing hypertrophy, fibrosis, inflammation, and oxidative stress, finally leading to cardiac hypertrophy and AF." (PMID 32595507, 2020). "Induction of TGF-β1 by high glucose or Ang-II, which then phosphorylates and activates downstream Smad2 and Smad3 proteins, results in cardiac fibrosis, cardiac hypertrophy and heart failure; however, Smad7 can antagonize TGF-β–mediated cardiac remodeling." (PMID 23690953, 2013). "At the mechanistic level, TGFBR1 gene silencing led to a reduction in myocardial collagen synthesis through the Smad2/3 signaling pathway and an inhibition of cardiac hypertrophy through the mitogen-activated protein kinase (MAPK) signaling pathway in HFpEF mice." (PMID 40880411, 2025). "The present study sought to evaluate the therapeutic potential of EVs derived from ADSCs and BMMSCs with and without transfection with Smad2/3 siRNA and of Smad2/3 siRNA alone in a hamster model of atherosclerosis-associated cardiac hypertrophy." (PMID 41154653, 2025). "The specific knockdown of Smad2/3 in activated fibroblasts can reduce the extent of cardiac fibrosis after pressure overload but cannot reverse myocardial hypertrophy and heart failure, whereas the specific knockdown of TGFBR1/2 can alleviate both cardiac fibrosis and hypertrophy." (PMID 36787190, 2023). "In addition, the enhanced SMAD2 phosphorylation exerted an inhibitory effect on cardiac hypertrophy." (PMID 36325361, 2022). "Moreover, mice with knockout of Smad4—a mediator of Smad2/3 nuclear translocation—develop cardiac hypertrophy, whereas overexpression of Smad2 attenuates cardiomyocyte hypertrophy." (PMID 29783655, 2018). "In the present study, Ang II was found to induce myocardial hypertrophy, fibrosis, oxidative stress, and inflammation, as evidenced by alterations in the PI3K/AKT1/mTOR/ERK, TGF-β/Smad2/3, NF-κB, and NOX1 signaling pathways." (PMID 39715792, 2025). "Elevated levels of TMAO further promote cardiac hypertrophy and fibrosis through the transforming growth factor-β-mothers against decapentaplegic homolog 2/3 (TGF-β-Smad2/3) signaling pathway, thereby inducing heart failure." (PMID 40709198, 2025). "These cells produce various proinflammatory cytokines and ROS that activates multiple signaling pathways (CaNA/STAT3, TGF-β1/Smad2/3, IKKɑ/NF-kB, and NOX1/4), thereby leading to cardiac hypertrophy, fibrosis, inflammation and DNA damage (cardiac remodeling)." (PMID 36467095, 2022). "Therefore, they exhibited upregulation of S100A8/A9, which led to exacerbation of inflammation, cardiac hypertrophy and fibrosis via activation of the NF-κB/NLRP3, AKT/Calcineurin A and TGF-β/Smad2 signaling pathways." (PMID 40860162, 2025).
cardiac hypertrophy (continued). "The results of the current study are consistent with the notion that cardiac hypertrophy is preceded by sharp upregulation in the mRNA expression levels of profibrotic markers (TGF-β, SMAD-2, SMAD-3, SMAD-4, and NF-κβ) and marked downregulation of antifibrotic SMAD-7 mRNA and let-7b miRNA." (PMID 36030321, 2022). "However, Sirt2-KO markedly exaggerated cardiac hypertrophy and fibrosis as well as decreases in cardiac ejection fraction and fractional shortening in aged (24-month-old) mice and Ang II-infused mice, which suggests a contradiction with the fact that SIRT2 helps SMAD2/3 activation." (PMID 37777567, 2023).